IL17A (interleukin 17A)
Diseases named in the same sentence as IL17A in open-access papers (continued):
Sharing a sentence is not in itself a finding about the gene and the disease.
hepatocellular carcinoma (135 papers, 2010 to 2026). A malignant tumor that arises from hepatocytes. "In particular, for patients at risk of hepatocellular carcinoma, IL-17A inhibitors have proven to be an effective and safe treatment option." (PMID 40861231, 2025). "The IL17A SNP has been reported as a risk factor for developing hepatitis B virus-associated hepatocellular carcinoma in the Chinese Han population." (PMID 36556060, 2022). "We previously demonstrated that interleukin‐17A (IL‐17A) is associated with the progression of hepatocellular carcinoma (HCC)." (PMID 29689643, 2018). "In stratified analyses by cancer types, we found the IL-17A overexpression was significantly associated with decreased OS in hepatic carcinoma and NSCLC, but with improved OS in ESCC." (PMID 29029520, 2017). "IL-17A has been proven to be associated with the progression of hepatocellular carcinoma." (PMID 40861231, 2025). "Polymorphisms in IL17A, which control IL-17 A production, may affect hepatocellular carcinoma risk in patients with persistent HBV infection." (PMID 37946175, 2023). "In addition, in stratified analyses by cancer types, IL-17A overexpression was significantly associated with worse OS in hepatic carcinoma, but with improved OS in esophageal squamous cell carcinoma (ESCC)." (PMID 29029520, 2017). "It is widely reported that IL-17A and IL-17F polymorphic variants are correlated with increased susceptibility to several digestive system primary malignancies, such as gastric cancer, esophageal cancer, hepatocellular carcinoma, and oral squamous cell carcinoma." (PMID 35410225, 2022). "Cytokines such as interleukin-17A (IL-17A) was shown to cause metastasis in hepatocellular carcinoma (HCC) by upregulating the levels of metalloproteinases (MMP) 2 and 9 through NF-κB induction." (PMID 33375283, 2020). "Studies have shown that IL-17A promotes carcinogenesis by inhibiting autophagic cell death in hepatocellular carcinoma and stimulates the invasion-metastasis cascade by activating AKT signaling." (PMID 40861231, 2025). "For example, IL-17A secreted by lymphatic endothelial cells promotes the self-renewal and immune escape of hepatoma stem cells in liver cancer." (PMID 39840048, 2024). "But only one study has reported that IL‐17A secreted from lymphatic endothelial cells promotes tumorigenesis by upregulation of PD‐L1 in hepatoma stem cells in vitro so far." (PMID 37153113, 2023). "IL‐17A promotes immune escape of hepatoma stem cells partly through upregulation of PD‐L1 expression." (PMID 37153113, 2023). "IL-17A, secreted in concert from lymphatic endothelial cells, promotes tumorigenesis by upregulation of PD-L1 in hepatoma stem cells." (PMID 35008390, 2022). "It was also reported that IL-17A activates the IL-6/STAT3 signal pathway followed by cell proliferation in hepatocellular carcinoma." (PMID 34445513, 2021). "The role of IL-17A has also been investigated in other tumor types such as colorectal, esophageal squamous cells carcinoma, ovary and hepatocellular carcinoma." (PMID 28715437, 2017). "In hepatocellular carcinoma and fibrosarcoma, IL-17A promotes tumor progression through potentiating angiogenesis and metastasis." (PMID 28035060, 2017). "IL-17A potentiates metastasis of hepatocellular carcinoma cells and increases tumor resistance to vascular endothelial growth factor (VEGF) inhibition therapy, which makes it hard to treat certain types of cancers." (PMID 28035060, 2017). "Indeed, this study demonstrated that low-dose pre-irradiation of tumor beds subsequently enhanced implanted-hepatoma growth in vivo, which was suppressed by IL-17A neutralization." (PMID 25181290, 2014). "Interestingly, studies in patients with hepatocellular carcinoma revealed a higher number of IL-17 expressing lymphocytes in tumor tissue, which correlates with reduced survival, suggesting IL-17 a tumor promoting role." (PMID 20374638, 2010).
hepatocellular carcinoma (continued). "Blocking IL-17A and inhibiting Th17 cell differentiation in mice has demonstrated prevention of MASH and hepatocellular carcinoma (HCC), showcasing the therapeutic promise of IL-17A blockers." (PMID 40977717, 2025). "Inhibition of IL‐17A signaling may be a promising approach for hepatoma treatment." (PMID 37153113, 2023). "Our earlier studies found that intra-tumoral IL-17A-producing T cells (Th17) could promote tumor progression by fostering angiogenesis in hepatocellular carcinoma; whereas, mast cells expressing IL-17A in the muscularis propria predicted a favorable prognosis in esophageal squamous cell carcinoma." (PMID 26840565, 2016). "The aim of this study is to investigate the effect of IL-17A on the progression of hepatocellular carcinoma (HCC)." (PMID 21760911, 2011). "Moreover, it is known that hepatic steatosis, inflammation, fibrosis, and finally hepatocellular carcinoma (HCC), induced by alcohol are critically regulated by IL-17A." (PMID 37373022, 2023). "Previous reports showed that IL-17A-induced STAT3 activation promotes tumor progression and angiogenesis in hepatocellular carcinoma and non-small-cell lung cancer, respectively." (PMID 32492770, 2020). "On the contrary, IL-17A inhibited autophagy via TAB2/TAB3-p38 mitogen-activated protein kinase pathways and mTOR signaling in Hepatocellular carcinoma (HCC) cells and keratinocytes." (PMID 31921197, 2019). "In addition, IL17A influences liver disease by modulating immune responses, with increased levels of IL17A correlating with worsening liver disease in MASH and hepatocellular carcinoma (HCC)." (PMID 39459627, 2024). "Meanwhile, it increased NK cells’ cytotoxicity in spleen, down-regulated the amount of CD4+CD25+Foxp3+ Treg cells and Th17 cells in tumor tissue, and decreased IL-10, TGF-β, and IL-17A levels (P < 0.01) whereas increased IL-2 and IFN-γ levels (P < 0.01) in the serum of hepatoma H22-bearing mice." (PMID 28086772, 2017).
pneumonia (133 papers, 2010 to 2025). An acute, acute and chronic, or chronic inflammation focally or diffusely affecting the lung parenchyma, caused by an infection in one or both of the lungs (by bacteria, viruses, fungi, or mycoplasma.). "It simultaneously synergizes with IL-17A and IL-17F to induce antimicrobial peptide expression in epithelial cells and mediate an early mucosal defense response to pneumonia-causing microorganisms in a mouse model." (PMID 36233337, 2022). "It has been demonstrated that Th17 cells and IL-17A are protective against certain pulmonary infections in murine models of pneumonia but the role for these factors in determining the risk for nosocomial pulmonary infections in humans is unclear." (PMID 28806403, 2017). "Although elevated IL-17A levels have been linked to poor pneumonia outcomes, this cytokine is important for the clearance of intracellular pathogens and its premature collapse may hinder host defense." (PMID 40869413, 2025). "In addition, IL-17A showed limited predictive power for the risk of severe pneumonia (P < 0.05, AUC:0.712 with 95% CI:0.556–0.839)." (PMID 36793128, 2023). "Neonatal S. pneumoniae lung infection may promote the development of allergic asthma in adulthood in association with enhanced IL-17A production." (PMID 25816135, 2015). "In HIV patients with pneumonia, increases in the relative abundance of Prevotella are associated with a unique metabolomic fingerprint (enriched with amino acid metabolites and monoacylglycerols), a pro-inflammatory milieu with increased IL-17A and an increased risk for mortality." (PMID 35643931, 2022). "Significant differences between genotypes that exceeded 1.5-fold in male mice with S. pneumoniae pneumonia include higher concentrations of IFNγ, IL-12 (p40), IL-17A and MCP-1 (CCL2) in HRB-Mertk-/- compared to wild type males." (PMID 40238852, 2025). "In summary, we demonstrated that the intranasal EPS301-adjuvanted vaccination provided effective and sustained protection against P. aeruginosa induced pneumonia in an IL-17A–dependent manner." (PMID 39556597, 2024). "IL-17A total intensity expression was reduced on Day 21 post-infection in these pulmonary compartments and in granulomas and pneumonia, where some cells with macrophage and lymphocyte morphology were positive." (PMID 39024223, 2024). "In our study, we performed a correlation analysis in the group of patients with HIV and pneumonia, evaluating the cytokines IL-6, IL-17A, MCP1/CCL2, PAI1, IL-1β, and VEGF/VPF in relation to key parameters of lung function." (PMID 38251391, 2024). "Seven hub genes, IL4, IL6, CSF2, IFNG, IL1B, TNF and IL17A, were responsible for Experimental Lung Inflammation, Pneumonitis, Pneumonia and Lobar Pneumonia." (PMID 36989283, 2023). "In the current study, we have shown that IL-17A was positively correlated with the severity of pneumonia in children and contributed to airway dysfunctions in a murine model with RSV infection." (PMID 36793128, 2023). "IL-17A increased significantly in RSV-infected children and was positively associated with pneumonia severity." (PMID 36793128, 2023). "Most studies have shown that in tumors and inflammatory diseases, such as in children with pneumonia, cell damage or other inflammatory factors such as IL-17A can activate the expression of S100a8/a9 through the IL-17 signaling pathway." (PMID 35741040, 2022). "Single-cell studies identify IL-17A-producing γδ T (Tγδ17) cells with a phenotype of TCRγδhiCD3hiAQP3hiCXCR6hi in both infected mice and patients with pneumonia." (PMID 33772013, 2021). "Vγ9Vδ2 cells, a major IL-17A-producing γδ T cell population in human, significantly increased in BLF, associated negatively with pneumonia severity." (PMID 33772013, 2021). "Low levels of IL-1β were only seen in 2 patients with severe pneumonia and low levels of IL-17A in 2/8 patients with severe pneumonia, and 7/14 in mild illness." (PMID 33199778, 2020).
pneumonia (continued). "Analysis of BAL fluid in children with pneumonia revealed IL-17F to be more abundantly expressed than IL-17A." (PMID 33329560, 2020). "Proinflammatory cytokines such as IFN-γ, IL-4, IL-17A, and IL-10 play important roles in the immunization process against S. pneumonia." (PMID 29375585, 2017). "The adaptive-immunity (Th1/Th17)-related CXCL10/IP-10, CXCL9/MIG and IL-17A however, were markedly suppressed in severe pH1N1 pneumonia (2–27 times lower than seasonal influenza; P−values<0.01)." (PMID 22022504, 2011). "With advances in nanotechnology, Noh and colleagues developed cellular nanodiscs derived from P. aeruginosa OMVs, which enhanced both cellular and humoral immune responses, protecting against pneumonia by reducing the lung bacterial loads and pro-inflammatory cytokines (IL-12, IL-17A and TNF-α)." (PMID 40076637, 2025). "IL-17A is an early marker in severe infections, including in pneumonia that might progress to respiratory distress." (PMID 41379768, 2025). "Relative to controls, cytokines that were significantly elevated in the pneumonia cohort at 24 and/or 48 h after inoculation (evolution phase) were IL‐1β, IL‐6, IL‐15, IL‐16, IL‐17a, IP‐10, MCP‐1, MIP‐1β, and TARC; IL‐5 was significantly elevated at 168 h (resolution phase)." (PMID 40947770, 2025). "Compared with encephalitis with headache symptoms group and pneumonia without headache symptoms group the serum levels of IL-4, TNF-α, IL-17A, and IL-12p70 were higher in migraine group than in pneumonia group, and the levels of IL-12p70 were higher than those in encephalitis group (p < 0.05)." (PMID 38356891, 2024). "Intriguingly, IL-17A knockout mice exhibited lower survival rates, impaired bacterial clearance ability, and exacerbated lung tissue damage upon EPS301 adjuvanted vaccination against P. aeruginosa-induced pneumonia, indicating an IL-17A-dependent protective mechanism." (PMID 39556597, 2024). "In contrast, infection with the highly virulent strain 04–303 induced two peaks of IL-17A mRNA expression, on Days 1 and 14 of infection (the latter also being the day on which pneumonia started), and 1 week later, expression was extensive and associated with necrosis and high mortality." (PMID 39024223, 2024). "Among RSV infection group, IL-17A was positively related to the severity of pneumonia (P < 0.05)." (PMID 36793128, 2023). "Furthermore, the activation of the IL-23 signaling pathway, mediated by IL-17A, promoted antibacterial responses, neutrophil activation, and pneumonia." (PMID 38098038, 2023). "Activation of NLRC4 stimulates the production of IL-1 β, IL-17A, and neutrophil chemoattractants in the lung, which prove beneficial to the host during pneumonia caused by Gram-negative bacteria such as K. pneumoniae and P. aeruginosa." (PMID 34737734, 2021). "Also, ILC3 produce IL-17A, which enhances the phagocytic uptake and killing of the bacteria by pulmonary macrophages to clear pneumonia." (PMID 32849610, 2020). "Furthermore, necropsy examinations also indicated significantly alleviated pneumonia lesions at 5 and 7 dpi in IL-17A knock-out mice infected with PR8 virus." (PMID 31681209, 2019). "In addition, the levels of IL-4, IL-5, IL-13, and IL-17A in BALF were also significantly higher in the pneumonia group." (PMID 30723734, 2019). "To study whether a similar dampening of the IL-17 response to infection exists in VAP patients, we studied IL-17A in VAP patients on the day of VAP diagnosis compared to patients that were admitted to the ICU with pre-existing pneumonia." (PMID 31614857, 2019). "In the present study, the cytokines, TNF, IL-1β, IL-6, IL-8, IL-12p70, IFN-γ, IL-17A, IL-10 and IL-5, were detected in the serum of children with pneumonia and severe pneumonia at hospital admission, and IL-6 was the only cytokine associated with disease severity." (PMID 27905908, 2016).
pneumonia (continued). "Furthermore, using a model of resolving pneumonia, we found significantly lower concentrations of IL-17A in the lungs of mice infected with PLN-A compared to those infected with wild-type pneumococci, at both 24 and 48 hours post-infection." (PMID 21085613, 2010). "Thus, neonatal S. pneumoniae lung infection exacerbates the hallmark features of AAD in adulthood, which may be associated with increased IL-17A production." (PMID 25816135, 2015). "Consistent with previous studies, our study demonstrated that IL-17A in NPAs were significantly higher in RSV-infected children than in the control group and were positively correlated to the severity of pneumonia related to RSV infection." (PMID 36793128, 2023). "The deletion of IL-17a results in significant neutrophilic inflammation and increased mortality in mice with USA300 pneumonia." (PMID 36830716, 2023). "In a model of bleomycin-induced pneumonia, IL22 was shown to lose its protective effect and instead promoted airway inflammation in the presence of IL17A." (PMID 37189778, 2023). "Similar to the antibody responses we observed, there were higher numbers of S. aureus-specific IL-17A and IFNγ-secreting T cells following SSTI, compared with pneumonia, at 4 weeks post-infection." (PMID 35983063, 2022). "In view of our finding (above) that resistance to S. aureus-induced pneumonia was promoted by rMntC-EPS30-induced IL-17A, we attempted to determine which immune cell population(s) were responsible for IL-17A production." (PMID 34358191, 2021). "The prediction capability of IL-4/IL-17A was greater than that of other commonly used indicators, including NLR (AUC = 0.897), oxygenation index (AUC = 0.795), CURB-65 (AUC = 0.795), and pneumonia severity index (PSI) (AUC = 0.786)." (PMID 34692846, 2021). "During S. pneumoniae lung infection, the depletion of ILC3s protects the host from ALI due to inhibition of IL-22 and IL-17A production." (PMID 32849610, 2020). "The authors also showed increased levels of IL-17A and CD4+ cells in lungs of previously colonized mice, indicating a potential role for T cell mediated immunity for prevention of pneumonia." (PMID 30881363, 2019). "The main phenotype of Clca1−/− mice in a model of S. aureus-induced pneumonia consisted of reduced activation of CXCL-1 and IL-17A expression and decreased neutrophilic infiltration into the bronchoalveolar space." (PMID 29610986, 2018). "In patients with pandemic H1N1 pneumonia, the adaptive Th1/Th17-immunity related cytokines (e.g. IP-10, MIG, IL-17A) were markedly suppressed." (PMID 23185463, 2012). "There was sustained activation of the proinflammatory cytokines (IL-6, CXCL8/IL-8, CCL2/MCP-1, sTNFR-1) in severe pH1N1 pneumonia; the CXCL10/IP-10, CXCL9/MIG and IL-17A responses remained largely suppressed during the hospital course." (PMID 22022504, 2011). "The key findings were as follows: the serum levels of IL-4, TNF-α, IL-17A, and IL-12p70 were higher than those in the pneumonia without headache group, and the serum level of IL-12p70 was higher than that in the encephalitis with headache group." (PMID 38356891, 2024). "The high concentration of IL-6, IL-17A, GM-CSF, and IFN-γ were found in the BAL liquid phase which may account for the volumetric inflammatory changes in severe patients with pneumonia." (PMID 37626620, 2023). "In contrast, pneumonia did not result in increased accumulation of IL-17A and IFNγ-producing T cells specific for Hla, LukE, or LukS-PV in the spleen." (PMID 35983063, 2022). "Again, both groups showed same survival rates, suggesting that Il17a is not required for the resistance against pneumonia induced by PMBL." (PMID 33981296, 2021). "We found that high levels of IL-6, IFN-γ, and IL-2 and low levels of IL-5, IL-25, IL-17A, and IL-22 were found in the severe pneumonia group compared to the nonsevere pneumonia group." (PMID 34692846, 2021).